CD68 (CD68 molecule)
Diseases named in the same sentence as CD68 in open-access papers (continued):
Sharing a sentence is not in itself a finding about the gene and the disease.
tumor (continued). "Further analysis of the combined prognostic value of the infiltrating density of CD68+ macrophages in tumor nest and stroma, showed varying degree of death risk ranging from high to medium to low." (PMID 27736796, 2016). "Taken together, the results of our pooled analysis support that a higher density of either CD68+ or CD163+ TAMs in the tumor microenvironment of adult cHL is associated with a higher risk of worst outcome." (PMID 27745550, 2016). "We suggest that tumor associated macrophages (CD68+ TAMs) present in baseline biopsies were tumorigenic and supported disease progression as has been suggested in the literature." (PMID 26981247, 2016). "Some studies have indicated that a high density of either CD68+ or CD163+ TAMs in the tumor microenvironment of adult cHL is associated with poorer outcomes." (PMID 27745550, 2016). "In the OSCC specimens, we found that the high number of CD68-positive macrophages in tumor nest was positively associated with tumor location and mortality." (PMID 26769084, 2016). "The number of CD68+ macrophages was found to be associated with tumor depth and stage (p = 0.001 and p = 0.043, respectively)." (PMID 26226629, 2015). "We found that peritumoral CD68(+) macrophages were also up-regulated on the seventh week of tumor growth; this change was significantly associated with peritumoral IL-6R (rr = 0.556, P = 0.001)." (PMID 26525581, 2015). "A high abundance of CD68 in TIF was correlated not only with a higher risk of overall tumor recurrence but also with local tumor recurrence." (PMID 26497197, 2015). "Instead, CD34+ vessel number was positively associated with the presence of CD68 in tumor stroma, furthering the notion that S100A9 promotes angiogenesis in vivo through increased macrophage recruitment." (PMID 26315114, 2015). "The density of CD68+ macrophages in the tumor tissue was negatively associated with overall survival (p = 0.0073)." (PMID 26226629, 2015). "Differences were mainly found for CD68, a marker of tumor associated macrophages, which have been linked to tumor progression and worse prognosis both in experimental models and clinical series." (PMID 25432519, 2014). "vi) A tumor-related localization of CD68+ (H2) and CD163+ (I2) macrophages was associated with a high abundance of myofibroblasts (L2)." (PMID 24797069, 2014). "The number of infiltrated tumor-associated macrophages (TAMs) stained by anti-CD68 antibody in xenograft liver tumor was significantly reduced after Ad-ANGPTL4 treatment." (PMID 25148701, 2014). "Further, a significant fraction of the CK + CD45+ events also expressed CD68, a marker associated with tumor-associated macrophages." (PMID 24602188, 2014). "CD68 is a macrophage marker for tumor-associated macrophage that plays an important role in angiogenesis and metastasis." (PMID 24842612, 2014). "CD68+ tumor-associated macrophages were recently shown to be associated with adverse outcomes, including shortened survival, which is a consequence of primary refractory and early relapsing cHL." (PMID 23988031, 2013). "A number of previous reports showed that CD68+ tumor-associated macrophages are a poor outcome marker of cHL." (PMID 23988031, 2013). "Another study has shown that the moderate or strong expression of VEGF is significantly associated with a high MVD and an increased number of CD68+ macrophages for aggressive tumor subgroups." (PMID 24137338, 2013). "More CD68+ tumor-associated macrophages were present in the PO group than in either the GO group or among normal controls." (PMID 23988031, 2013). "Our results also revealed that a large number of CD68+ tumor-associated macrophages were present in the tumor microenvironment of poor outcome tissue samples in which the CD30+ cells overexpressed both SDC1 and FGF2." (PMID 23988031, 2013). "The tumor-associated macrophages were detected using an antibody against CD68, a pan-macrophage marker frequently used as a marker for TAMs." (PMID 24098773, 2013).
tumor (continued). "In conclusion, we determined that CD163 is a better marker than CD68 for the enumeration of tumor associated macrophages in the everyday practice of surgical pathology." (PMID 22289504, 2012). "Actually, the association of CD68+ TAMs with hypoxia is not only in irradiated tumors, but also occurs in tumors growing from pre-irradiated tumor bed, so-called pre-IR tumor." (PMID 22888475, 2012). "Association of tumor-associated macrophages (TAM) CD68+ with adverse clinical outcomes has been confirmed in several studies in hematologic and solid tumors." (PMID 22927872, 2012). "Tumour CD8+ infiltrate was directly associated with CD68+ infiltration (P<0.01), CD34+ (P<0.05) and neo-adjuvant therapy (P<0.05)." (PMID 22240784, 2012). "We investigated the angiogenesis, lymphangiogenesis, and CD11b+/CD68+ tumor-associated macrophages (TAM) by using immunofluorescence staining." (PMID 21481239, 2011). "The reduction in CD68 positive cells in CR tumor is also associated with significant reductions in the protein expression of CD68 in tumor tissues as detected by western blot." (PMID 21479220, 2011). "Calculation of the integrated score for an individual risk (ISIR), considering tumour size (T), lymph node status (N), metastasis (M), Gas6 and CD68 identified 82% of patients as having a clear risk status." (PMID 21794149, 2011). "In all of the patient biopsies, CD68-positive tumour-associated macrophages presented a mixed CXCL10 (M1)/CD163 (M2) pattern, expressed CXCR4, GM-CSF and HB-EGF, and some stained positive for CXCL12." (PMID 20946648, 2010). "The presence of CD105-positive vessels in the tumour was significantly associated with total (stroma and epithelial cell clusters) number of CD68-positive cells (P=0.004)." (PMID 19352388, 2009). "Tumour-associated macrophages CD68+ were positively correlated with tumour CD4+ (P<0.01) and CD8+ (P<0.001) T lymphocytes." (PMID 18797461, 2008). "Hybridisation was most marked in macrophage-rich regions of these tumours and was seen to correspond with tumour-associated macrophages (CD-68) upon immunostaining of serial sections." (PMID 12942123, 2003). "However, Tie2-/CD14+ macrophages and CD68+ tumor-associated macrophages (TAMs) showed uniform stromal distribution." (PMID 42074283, 2026). "Clinical cohort studies have also demonstrated that increased total TAM density in NSCLC tissues and elevated ratios of the M2 marker CD163 to the pan‐macrophage marker CD68 (i.e., CD163/CD68 ratio) are associated with advanced tumor stage, higher metastatic risk, and poor prognosis." (PMID 41426206, 2026). "An associated depletion of CD68‐positive macrophages upon the addition of anti‐ROR1 CAR T‐cells showed that CAR T‐cell‐mediated cytotoxicity was extended to cells involved in the immune component of the tumor model microenvironment." (PMID 40249196, 2025). "In addition, immunohistochemical (IHC) staining was performed on tumor tissues to evaluate the expression of inflammation- and malignancy-associated markers, including CD68, MCP-1, MPO, and TGF-β." (PMID 41012537, 2025). "The increased protein expression of CD68 in tumor-associated antigen presenting cells could indicate enhanced phagocytic activity." (PMID 40395327, 2025). "However, the concurrent enrichment of CD68+CD163+ tumor-associated macrophages and upregulation of macrophage-related signatures indicate a possibly immunosuppressive microenvironment." (PMID 40859352, 2025). "Interestingly, the presence of both FAP + CAFs, T-cyts (CD8 +), T-regs (CD4 + FOXP3 +), and macrophages (CD68 +) above P75 (log-rank p = 0.016) at the tumor center was associated with worse CSS." (PMID 39751643, 2025). "In this analysis, we additionally found that immune cells (CD4, CD8, and CD68) had an increased distance to tumor cells in HIV-associated tumors, using Euclidean distance as well as neighborhood enrichment analysis in order to assess the spatial relationships between different cell types." (PMID 40459946, 2025).
tumor (continued). "Similarly, values equal to or higher than the P50 values for CD68 + at the tumor center were also associated with worse CSS." (PMID 39751643, 2025). "In COAD, low CD68 expression was associated with improved OS, suggesting that high levels of CD68 may promote tumor progression, possibly through increased macrophage infiltration and pro-tumorigenic signaling." (PMID 40918116, 2025). "Furthermore, immunofluorescence (IF) staining demonstrated co-localization of ALDOA with CD68 + tumor-associated macrophages (TAMs), suggesting a possible link between ALDOA expression and the immunosuppressive tumor microenvironment." (PMID 41239433, 2025). "In addition, the enrichment of CD8+ T cells, CD20+ B cells, CD56+ natural killer cells and CD11c+ dendritic cells, and decreased infiltration of CD68+CD163+ tumor-associated macrophages, were only observed in MPR patients after NAIC." (PMID 40295492, 2025). "The presence of high CD68+ CAFs was linked to tumor initiation." (PMID 40656546, 2025). "Interestingly, LAMP-4 (CD68) is associated with tumor immunity in the TME, as LAMP-4 levels are positively related to immune cell infiltration, such as dendritic cells, macrophages, monocytes, and neutrophils." (PMID 40277899, 2025). "Similarly, melanomas with dense CD163+ cell infiltration in the tumor stroma, and CD68+ infiltration at the tumor front were associated with poorer OS." (PMID 39825956, 2025). "The same was observed for CD68+ staining, the tumor-associated macrophages (TAMs) marker." (PMID 40006917, 2025). "Additionally, CD68+ cells which represented tumor-associated macrophages (TAMs) significantly reduced after PD-1 blockade plus CRT." (PMID 38462629, 2024). "In addition, the proportion of CD8+ lymphocytes in all tumor-infiltrating CD3+ lymphocytes (TILs) was the highest in this patient, while the proportion of tumor-associated CD68+ macrophages (TAMs) was the lowest." (PMID 38383419, 2024). "CRP may engage with immunosuppressive cells, such as CD68+ tumor‐associated macrophages and CD15+ tumor‐associated neutrophils (TANs), contributing to a suppressed tumor immune microenvironment." (PMID 38923354, 2024). "Similarly, we discovered that CD68+ PLIN2+ tumor-associated macrophages induced immune suppression, accompanied by high levels of immune checkpoint molecules." (PMID 38554152, 2024). "In addition, we found that the expression of PCDHGA10 was related to CD68+ tumor-associated macrophages (TAMs)." (PMID 39687617, 2024). "CD68+ tumor-associated macrophages (TAM) are the most abundant cell type in the TME of PC." (PMID 39635522, 2024). "Moreover, CD45-positive regions of tumor-infiltrating lymphocytes (TILs) were identified in 125 (96.89%) samples, and 128 (99.22%) cases showed CD68-positive regions of tumor-associated macrophages (TAMs)." (PMID 38833004, 2024). "Our results show that tumor-associated myeloid cells (CD68+) may contribute to the NRG1 pool seen in these tumors." (PMID 39210279, 2024). "In our study, CD68+ macrophage infiltration was significantly associated with poorer survival outcomes, supporting the notion that tumor-associated macrophages (TAMs) contribute to a more aggressive tumor phenotype." (PMID 39330005, 2024). "In addition, a high density of CD68+ tumor macrophages have been associated with a better median cancer-specific survival, median overall survival, and lower risk of recurrence." (PMID 38691575, 2024). "Additionally, patients with high TBC1D1 expression exhibited increased infiltration of M2 tumor-associated macrophages (TAMs), showing significant elevation in markers including CD68 and ARG1." (PMID 38529286, 2024). "The presence of CD68, recognized as a marker reflecting the overall infiltration of TAMs in tumors, is associated with a tumor-promoting role of CD68 + TAMs in the context of tumor progression." (PMID 38273373, 2024).
tumor (continued). "In addition, the different cell populations found in the T18_IM RB derived stromal cell line were successfully separated using MACS separation for tumor-associated macrophages (CD163 + CD68) and glia (GFAP)." (PMID 39695086, 2024). "Recent studies have shown that CD68+ is overexpressed in tumor associated macrophages (TAMs)." (PMID 38822345, 2024). "In addition, B7-H4+ tumors in the isotype group have high expression of immunosuppressive genes including Tgfbr1 (TGFβ receptor), Cd33, and CD68 (tumor-associated macrophage markers)." (PMID 38687247, 2024). "In addition, CD68 has also been identified as a marker for M1 macrophages, which have anti-tumor functions and are associated with a favorable prognosis in some cancers." (PMID 38357542, 2024). "In addition, a team reported higher densities of CD3+ lymphocytes and CD68+ tumor‐associated macrophages after chemotherapy in the tumor immune microenvironment." (PMID 37676094, 2023). "A meta-analysis of 29 studies demonstrated that high infiltration of CD68+ pan-macrophages at invasive margins was significantly associated with better survival, while high infiltration of M2-macrophages in tumor center was significantly associated with poor prognosis in CRC patients." (PMID 37342343, 2023). "On the other hand, mRNA expression of Ccl2 (macrophage chemotaxis marker), Cd68 (tumor associated macrophages, TAMs), Cd163 (M2 TAMs) and Foxp3 (regulatory T cells, Tregs) markers was greatly increased in LLC control mice, while this increment was less pronounced in 6-thio-dG-treated mice." (PMID 37085672, 2023). "In addition, a spatial analysis revealed a correlation between the abundance of PD-L1+CD68+ tumor-associated macrophages and PD-1+CD8+T cell infiltration, indicating pro-tumor immunity associated with a poor prognosis." (PMID 36900182, 2023). "Tzankov and colleagues found a direct association of CD68+ macrophages with PD-1+ and GrB+ immune cells within tumor microenvironment, demonstrating that an immunohistochemistry-based score considering all of these three cell types had independent prognostic significance." (PMID 36910620, 2023). "Interestingly, bioinformatic prediction and immunohistochemical/immunofluorescence staining analysis revealed that BCL2A1 expression was obviously associated with the tumor-associated macrophages (TAMs) markers CD68 and CCL2." (PMID 37889551, 2023). "We showed here that MSLN reshapes the immune matrix of the tumor microenvironment, recruiting T cells CD8+ and macrophages CD68+, increasing the collagen type I protein, and contributes to the establishment of functional and mechanical anti-tumor barrier in MPM mitigating the risk of death." (PMID 37901248, 2023). "HIF-2α and CD68+ tumor-associated macrophages resided in areas with high VEGF in the perivascular niche of neuroblastoma tumors, suggesting that they may be facilitating angiogenesis at these sites." (PMID 37124241, 2023). "Tumor-associated macrophages (TAMs, CD68+) are elevated in many cancers." (PMID 37109686, 2023). "Furthermore, within the interface of the untreated PDOX, we observed proliferating (MKI67-positive) tumour cells in close proximity to Cd68-expressing tumour-associated microglia and Gfap-expressing astrocytes, similar to drug-treated PDOX." (PMID 37127652, 2023). "Furthermore, a spatial analysis revealed that the abundance of PD-L1+CD68+ tumor-associated macrophages correlated with PD-1+CD8+ T cell infiltration levels." (PMID 36900182, 2023). "CD68 tumor‐associated macrophages were counted and dichotomized." (PMID 36598153, 2023). "CD68 is overexpressed in tumor-associated macrophages (TAM)." (PMID 36980787, 2023). "Analysis of multiplex staining images in the primary cohort indicated that Siglec-15 and PD-L1 expressions could be detected in both TCs and tumor-associated stromal cells, including CD68+ macrophages (eFigure 2A in Supplement 1)." (PMID 36648946, 2023).
tumor (continued). "Both CD3 + /CD4 + and CD3 + /CD8 + T-cell as well as CD68 + /CD163 + hot tumours were significantly associated with high PD-L1 expression scores, which might be relevant for therapy of squamous bladder cancer with pembrolizumab." (PMID 36726072, 2023). "Although the clinical prognosis and immune infiltration associated with high CD68 expression levels vary by tumor type, inhibition of CD68-dependent signaling may be a promising therapeutic strategy for cancer immunotherapy." (PMID 37790755, 2023). "In a Bulgarian cohort conducted on 210 patients with primary CRC, a lower density of CD68+ TAMs in the invasive tumor front which is considerably associated with the advanced tumor stage (III and IV stages), distant metastases, and local lymph nodes specific metastases was observed." (PMID 37525217, 2023). "In addition, the recruitment of CD68+ monocytes and macrophage subsets into the tumor bed is usually associated with a poor prognosis, although this has not been shown to be statistically significant." (PMID 37835544, 2023). "CD68 is connected to the family of lysosomal-associated membrane proteins and is famous for being a routine immune marker of cells of monocyte/macrophage lineage use, which has various functions in immunity, tumor biology, and inflammation." (PMID 37048097, 2023). "In addition, high cholesterol diet-induced macrophage infiltration (CD68 positive cells) in tumor microenvironment, which was reduced by Cyp27A1 deficiency." (PMID 35379924, 2022). "SIRPα and CD68 were expressed, to a varying extent, by tumor-associated macrophages (Μφ, TAMs)." (PMID 35406573, 2022). "However, higher infiltration of CD8+PD-1+LAG-3+TIM-3+ T cells and CD68+ macrophages was associated with poorer OS with respect to tumour nests." (PMID 35982052, 2022). "Interestingly, CD68+ tumor‐associated macrophages (TAMs), which suppress or activate immune responses, were distributed in the center of the follicle." (PMID 35711130, 2022). "We further co-stained THBS2 with markers of cytotoxic T (CD8), Treg (FoxP3) and B (CD19) lymphocytes, as well as tumor-associated macrophages (CD68) 84 and nature killer (NK) cells (CD56) 85, which showed that immune cells were mainly located at the stromal compartment." (PMID 35547750, 2022). "Tumor‐infiltrating macrophages (CD68+ TAMs) are associated with tumor progression and low survival." (PMID 35711130, 2022). "CD163 and CD68 are factors linked with M2-polarized tumor-associated macrophages (TAMs)." (PMID 35454913, 2022). "For example, using MSI on tissue biopsies obtained from 66 patients with HCC revealed that high co-expression of CD38+ CD68+ on TAMs was associated with a better prognosis after surgery, in comparison to patients whose tumor only expressed a high density of CD68+." (PMID 35454766, 2022). "SIRPα and CD68 were expressed by tumor-associated macrophages (Μφ, TAMs)." (PMID 35406573, 2022). "CD68-specific antibody was used to stain tumor-associated macrophages in the KS tumor microarrays." (PMID 36560778, 2022). "Furthermore, EMR1-TC was significantly associated with CD68+ CD163+ tumor-associated macrophages (TAMs), and CRC with a high combined EMR1-TC+CD68+CD163+ score showed worse recurrence-free survival prognosis." (PMID 36551877, 2022). "We have aimed to study the five-year disease-specific survival (DSS) of newly diagnosed OPSCC patients dependent on the activation level of TILs measured by level of CD3 and Foxp3-positive TILs, as well as the level of tumor-associated macrophages (TAM) measured by CD68-positive cells." (PMID 35326661, 2022). "Moreover, it was demonstrated that high infiltration of CD68+TAMs in tumor stroma (TS) was linked to a higher TNM stage in OSCC." (PMID 35372038, 2022).